INS (insulin)
Diseases named in the same sentence as INS in open-access papers (continued):
Sharing a sentence is not in itself a finding about the gene and the disease.
hypertriglyceridemia (continued). "Moreover, it has been suggested that individuals exist who are not overweight, but who, like people with overt obesity, also have hyperinsulinemia, are insulin resistant, and are predisposed to hypertriglyceridemia, type 2 diabetes mellitus, and premature cardiovascular disease." (PMID 21134293, 2010). "The patient was managed conservatively with intravenous fluids for hydration and intravenous insulin for the severe hypertriglyceridemia and ketoacidosis." (PMID 41847627, 2026). "Prompt recognition is key, as the management of hypertriglyceridemia-induced pancreatitis differs significantly from more common etiologies and often includes insulin infusion or other triglyceride-lowering therapies." (PMID 41717162, 2026). "This case describes severe insulin-refractory hypertriglyceridemia with triglycerides consistently >4,000 mg/dL in a patient who presented with pleuritic chest pain but was otherwise hemodynamically stable, who had no clinical or radiographic pancreatitis." (PMID 41393592, 2025). "In the context of skeletal muscle-related IR, characterized by peripheral IR, hypertriglyceridemia has been known to impede insulin activity within the muscle and hinder glucose uptake." (PMID 40114229, 2025). "Hypertriglyceridemia can lead to the accumulation of lipid metabolites in hepatocytes, resulting in hepatic insulin resistance." (PMID 40664455, 2025). "We present a case of severe hypertriglyceridemia refractory to insulin, successfully managed with early therapeutic plasma exchange." (PMID 41393592, 2025). "The initial treatment of severe hypertriglyceridaemia typically involves rapid lipid reduction, often through insulin–dextrose infusions or plasmapheresis, in cases with impending pancreatitis." (PMID 40701175, 2025). "Four years later, during a second pregnancy, she presented with similar hypertriglyceridemia, managed with diet, metformin, fenofibrate, and insulin." (PMID 39949380, 2025). "The patient's hypertriglyceridemia was managed again with a continuous insulin IV infusion via peripheral venous access, O3FA, and fat restricted diet." (PMID 39949380, 2025). "Pharmacological management of very severe hypertriglyceridaemia with intravenous insulin and heparin therapy can rapidly decrease triglyceride levels." (PMID 41437989, 2025). "Insulin plays a pivotal role in managing severe hypertriglyceridemia by activating lipoprotein lipase (LPL), which facilitates the breakdown of triglycerides into free fatty acids." (PMID 39958046, 2025). "Saroglitazar has been shown to treat hypertriglyceridemia and improve insulin sensitivity, which are critical to MASLD therapy." (PMID 40130107, 2025). "In the intensive care unit (ICU), she received aggressive intravenous (IV) fluids and weight-based IV insulin, yet TG remained > 4,000 mg/dL, consistent with insulin-refractory hypertriglyceridemia." (PMID 41393592, 2025). "The proportion of patients who received intravenous insulin, broad-spectrum antibiotics, antifungal agents, and COVID-19 therapy was higher in the hypertriglyceridemia group than the comparator." (PMID 38449886, 2024). "Through treatment of her pancreatitis with intravenous insulin and plasmapheresis and subsequent transition to an oral regimen for her hypertriglyceridemia upon hospital discharge, the patient demonstrated full resolution of her ALI and coagulopathy." (PMID 39184768, 2024). "Conservative management was used for the pancreatitis, while hypertriglyceridemia was treated with an insulin infusion." (PMID 39011188, 2024). "Literature has reported the use of insulin perfusion to successfully treat acute pancreatitis in patients with severe hypertriglyceridemia (triglyceride level above 1,000 mg/dL)." (PMID 39114233, 2024). "Standard measures include insulin sensitizers, such as metformin, and lipid-lowering medications, such as statins or fibrates, in cases of severe hypertriglyceridemia." (PMID 38951919, 2024).
hypertriglyceridemia (continued). "For treating severe hyperglyceridemia, various insulin regimens, including continuous and intermittent infusions, are suggested." (PMID 39011188, 2024). "Chronic exposure to insulin drives very-low-density lipoprotein overproduction which leads to hypertriglyceridemia." (PMID 38535334, 2024). "Consistently, pharmacological interventions, such as fenofibrate alone or in combination with omega-3 fatty acids, improve insulin sensitivity in individuals with hypertriglyceridemia." (PMID 38611646, 2024). "In the second trimester, AGP reports kept improving [TIR 55%, TAR 44% (30 + 14), TBR 1% (1 + 0), GMI 7.6%] after increasing the insulin dose and resuming metformin, as well as the hypertriglyceridemia state (296 mg/dL)." (PMID 39479521, 2024). "Of note, treatment of DKA in itself can benefit hypertriglyceridemia-induced pancreatitis with the infusion of insulin." (PMID 39791034, 2024). "It leads to favorable changes in body composition, improved insulin sensitivity, hypertriglyceridemia, and transaminitis, reversing and limiting metabolic complications in patients refractory to standard medications for treating metabolic diseases." (PMID 39553096, 2024). "Animal experiments found that acetate can stimulate parasympathetic activity to increase ghrelin secretion and glucose-stimulated insulin secretion, thereby promoting overeating, hypertriglyceridemia, and increased liver and muscle fat storage." (PMID 39194508, 2024). "Specifically, compared to the control group, the expression of Cacna1c and Cacna1b, which was reported to be downregulated in hypertriglyceridemia subjects with decreased insulin secretion, was decreased in HFD mice." (PMID 38557554, 2024). "The patient was admitted to the intensive care unit (ICU) for DKA and hypertriglyceridemia-induced acute pancreatitis; he was continued on IV fluids and insulin drip with close monitoring of electrolytes and triglyceride levels." (PMID 39144851, 2024). "Insulin perfusion (8 U/hour) was started as a treatment for hypertriglyceridemia, and aspirin 100 mg was begun as secondary prevention." (PMID 39114233, 2024). "Global Sik2 knockout mice show impaired glucose and insulin tolerance, hypertriglyceridemia, and adipose tissue dysfunction, such as increased lipolysis and macrophage infiltration and decreased GLUT4 and adiponectin expression." (PMID 39081779, 2024). "IV fluid and insulin, followed by plasmapheresis, are the treatment of choice for necrotizing pancreatitis due to hypertriglyceridemia." (PMID 39429311, 2024). "On the other hand, excess visceral fat has been closely correlated with the impaired inhibition of free fatty acid release in response to insulin, along with hypertriglyceridemia and low HDL-C concentrations." (PMID 36741951, 2023). "Insulin deficiency is associated with accumulation of VLDL and chylomicrons leading to hypertriglyceridaemia, which is reversible with adequate insulin therapy." (PMID 37537394, 2023). "ApoC-III has been recently considered an important player in insulin resistance mechanisms, lipodystrophy, diabetic dyslipidemia, and postprandial hypertriglyceridemia (PPT)." (PMID 36689070, 2023). "Hypertriglyceridemia interferes with muscle glucose metabolism and is related to decreasing insulin sensitivity." (PMID 37759253, 2023). "This study aims to investigate the efficacy of insulin in treating severe hypertriglyceridaemia (HTG) during the third trimester of pregnancy." (PMID 36405614, 2022). "During early pregnancy, the increase in maternal fat depots is facilitated by insulin, followed by increased adipose tissue breakdown, and subsequent hypertriglyceridemia, mainly due to insulin resistance and estrogen effects." (PMID 34993347, 2022). "In this situation of hypertriglyceridemia, the action of insulin is blocked by inhibiting binding to its receptor, with a consequent reduction in hepatic glycogen synthesis and decreased glucose uptake by muscle." (PMID 35929905, 2022).
hypertriglyceridemia (continued). "Lipid metabolism in normal glucose-tolerant pregnancies differs from that in GDM pregnancies, where a rise of insulin promotes the maternal fat depots and increases the subsequent hypertriglyceridemia, due to insulin resistance and estrogen-like effects." (PMID 35631216, 2022). "In the insulin-resistant state, the alteration in LDL particles results in a predominance of small, dense LDL caused mainly by Hypertriglyceridemia." (PMID 35565871, 2022). "EPA which is a long-chain n-3 polyunsaturated fatty acid is reported to prevent hypertriglyceridemia and maintains insulin/glucose homeostasis." (PMID 35516426, 2022). "Obese individuals are insulin resistant and have disturbances in the metabolism of lipoproteins, being more pronounced in obese individuals with hypertriglyceridemia." (PMID 35929905, 2022). "Some adverse alterations in placenta do not modify the fetal phenotypic response to intrauterine supply restriction, but an insulin-resistant state and hypertriglyceridemia in fetuses are evidenced." (PMID 33499108, 2021). "This approach understandably needs more time to control hypertriglyceridemia and requires fine adjustment of the insulin dose." (PMID 33879184, 2021). "Hypertriglyceridemia was associated with markedly decreased serum levels of FGF21, a metabolic regulator with beneficial effects on glucose/lipid metabolism and insulin sensitivity." (PMID 34768942, 2021). "There are many confounding factors of HFD‐induced hypertriglyceridemia in animal models, including weight gain, body composition, and the levels of hormones such as leptin, insulin, and ghrelin." (PMID 33943005, 2021). "We found that moderate hypertriglyceridemia at the start of pregnancy was related to impaired insulin action and β-cell function." (PMID 33387029, 2021). "Resolution of euDKA and improvement of hypertriglyceridemia to less than 1,000 mg/dL occurred by day 6 and the patient was transitioned to subcutaneous basal-bolus insulin." (PMID 34853772, 2021). "Insulin therapy is routinely used to specifically treat hypertriglyceridaemia (HTG)-induced pancreatitis, characterised by plasma lipids exceeding 1,000 mg/dL (normal range, 101–150 mg/dL)." (PMID 34282152, 2021). "Hypertriglyceridemia at the start of pregnancy is closely related to impaired insulin action and β-cell function." (PMID 33387029, 2021). "Although insulin-sensitive participants also benefited from adipocytokines at the cognitive level, this effect disappeared in those with hypertriglyceridemia." (PMID 34731089, 2021). "IR leads to hypertriglyceridemia due to the inability of insulin to inhibit lipid production at the hepatic level." (PMID 34194826, 2021). "Hypertriglyceridemia at the start of pregnancy was closely related to impaired insulin action and β-cell function." (PMID 33387029, 2021). "During hypertriglyceridemia, triglycerides decrease glucokinase activity and glucose-stimulated insulin secretion in islets." (PMID 33490240, 2020). "Hypertriglyceridemia is also a therapeutic target in humans with AP, in whom heparin and insulin are used to lower serum triglyceride concentrations." (PMID 32893923, 2020). "Due to the adverse effect of hypertriglyceridemia on insulin sensitivity and islet beta cell function, more attention should be paid to the detection and management of hypertriglyceridemia." (PMID 32487177, 2020). "The pro-inflammatory molecules can affect the host metabolic process, as TNF-α was reported to decrease the insulin sensitivity and increase lipolysis in adipocytes, as well as IL-6 was found to contribute to hypertriglyceridemia." (PMID 32256675, 2020). "Strengths of our study include the fact that we compared two distinct metabolic phenotypes, i.e., lean insulin-sensitive and obese insulin-resistant individuals (with hypertriglyceridemia) and that within each group, the individuals were homogeneous." (PMID 31068904, 2019).
hypertriglyceridemia (continued). "In this study, we compared expression of genes of oxidative stress pathways in MNC following intake of HC, HF, and HP meals in a metabolically distinct cohort of lean insulin-sensitive and obese insulin-resistant individuals (with hypertriglyceridemia)." (PMID 31068904, 2019). "Fenofibrate, a PPAR-ά agonist is widely used drug in the management of hypertriglyceridemia that effectively reduces serum triglycerides levels and modestly improves insulin sensitivity." (PMID 31831868, 2019). "This is the first study to evaluate the effects of saroglitazar, a dual PPAR-α/γ agonist, on insulin sensitivity by hyperinsulinemic euglycemic clamp in patients of T2DM with hypertriglyceridemia." (PMID 31831868, 2019). "Intensive insulin therapy should be an effective, safe, available, and cheaper triglyceride-lowering therapy for hypertriglyceridemia-induced acute pancreatitis." (PMID 31215460, 2019). "We are presenting a case of pediatric DKA with hypertriglyceridemia and pancreatitis treated with extended insulin." (PMID 30891384, 2019). "We observed positive correlations between the postprandial serum insulin response with expression of pro- and antioxidant genes in the obese insulin resistant individuals (with hypertriglyceridemia)." (PMID 31068904, 2019). "Along with supportive care in AP, thereare additional options in hypertriglyceridemia AP, including heparin, insulin,apheresis, antioxidants, and fibrates." (PMID 30186885, 2018). "Based on the laboratory findings andimaging, we diagnosed acute pancreatitis (AP) secondary to hypertriglyceridemia.The patient was initiated on intravenous fluids and insulin to help decrease thetriglyceride level with the plan to initiate apheresis." (PMID 30186885, 2018). "In an RCT where patients with impaired glucose metabolism and coronary artery disease were supplemented with 1800 mg/day EPA for six months, postprandial hypertriglyceridemia, hyperglycemia, and insulin secretion were ameliorated compared to placebo." (PMID 30518065, 2018). "Insulin resis-tance is frequent from youth, the same as hypertriglyceridemia and low HDL-cholesterol." (PMID 29557732, 2018). "Some recent reports suggested a combination of intravenous heparin and insulin infusion in severe cases of gestational hypertriglyceridemia-induced AP, which increased the lipoprotein lipase activity." (PMID 29443736, 2018). "Many other investigators have reported that hypertriglyceridemia is closely related to an insulin resistant state." (PMID 29747616, 2018). "We successfully used heparin and insulin as first-line therapy in four consecutive patients with acute pancreatitis secondary to hypertriglyceridemia." (PMID 28225998, 2017). "All published cases of heparin and insulin therapy to control hypertriglyceridemia in HTGP also vouch for the safety and efficacy of this approach." (PMID 28225998, 2017). "Heparin and insulin have both been used also as monotherapy in the treatment of severe hypertriglyceridemia in previous studies." (PMID 28225998, 2017). "Several studies have shown that both hypertriglyceridemia and hypercholesteromia diminish glucose stimulated insulin secretion by inhibiting glucose oxidation via reducing pyruvate dehydrogenase (PDH) activity and elevating PDH kinase activity." (PMID 28199386, 2017). "Participants with only decreased insulin sensitivity who consumed high levels of alcohol were also more likely to have hypertriglyceridemia compared to abstainers." (PMID 27854254, 2016). "Lipoprotein lipase (LPL) gene knockout heterozygous mice, an animal model of genetic hypertriglyceridemia, exhibited significant insulin resistance, compensatory increased insulin secretion, and ultimately impaired glucose tolerance." (PMID 27034649, 2016). "Hypertriglyceridemia probably augments the effect of TG on the peripheral IR and reduces the percentage of mediating effect of 2-h insulin." (PMID 27814764, 2016).
hypertriglyceridemia (continued). "The present study showed that, in the hypertriglyceridemia patients with normal glucose tolerance, fenofibrate treatment significantly attenuated the increased insulin resistance and secreting load of islet β-cells." (PMID 27034649, 2016). "In view of the role of insulin in lipid metabolism and prevention of hypertriglyceridemia, it is plausible to propose a role of insulin in the hypolipidemic effect of honey." (PMID 26927161, 2016). "As a major constituent of added sugars, fructose has been shown to cause a variety of adverse metabolic effects, such as impaired insulin sensitivity, hypertriglyceridemia, and oxidative stress." (PMID 27322374, 2016). "This suggests that postprandial chylomicron particles probably play an important role in contributing towards postprandial hypertriglyceridaemia, together with apoB and insulin sensitivity." (PMID 26989412, 2016). "Hepatic fructose metabolism differs from glucose, and, in a hypercaloric setting, fructose induces hypertriglyceridemia and visceral adiposity, promotes lipogenesis and ectopic lipid accumulation, and decreases insulin sensitivity in humans as well as rodents." (PMID 27708683, 2016). "The n-3 PUFAs have been shown to reduce inflammation, enhance insulin sensitivity, and improve hypertriglyceridemia." (PMID 27651787, 2016). "Mice receiving an HFD exhibited hypertriglyceridaemia and hyperinsulinaemia, as both circulating triacylglycerol and insulin levels were significantly elevated compared with respective LFD controls." (PMID 26684450, 2016). "This study investigated the effects of hypertriglyceridemia and fenofibrate treatment on insulin sensitivity and β-cell function in subjects with normal glucose tolerance." (PMID 27034649, 2016). "This suggests that postprandial chylomicron particles have an important role to play in postprandial hypertriglyceridaemia, together with insulin sensitivity and apoB." (PMID 26989412, 2016). "Appropriate management of DKA with hypertriglyceridemia includes intravenous fluid and insulin administration according to DKA guideline, because the major mechanism of hypertriglyceridemia is insulin deficiency." (PMID 26904318, 2016). "In this study, we aimed to investigate the effects of hypertriglyceridemia and fenofibrate treatment on insulin sensitivity and β-cell function in subjects with normal glucose tolerance." (PMID 27034649, 2016). "Our HFD model showed serum hypertriglyceridemia and hypercholesterolemia, confirming insulin resistant conditions." (PMID 25977701, 2015). "Patients of newly diagnosed T2DM with hypertriglyceridemia were younger, fatter and had worse lipid profiles, glucose profiles, and high insulin levels than those with normal TG." (PMID 25924608, 2015). "We report the case a 44-year-old female with clinical acute pancreatitis secondary to hypertriglyceridemia who was successfully managed with the addition of intravenous insulin." (PMID 27785302, 2015). "Reduced leptin and insulin sensitivities contribute to hypertriglyceridemia induced by fructose ingestion." (PMID 24672546, 2014). "Different authors have proposed several different modalities for the treatment of hypertriglyceridemia, which includes plasmapheresis, infusion of heparin, and intravenous infusion of insulin and glucose." (PMID 24995138, 2014). "Heparin and insulin infusion are low cost alternatives to plasmapheresis but the first modality of choice for treatment of hypertriglyceridemia still remains conservative approach with nutritional and pharmacological methods." (PMID 24995138, 2014). "This study showed how the RQ increased during the combined administration of insulin/glucose together with fat, which is a condition similar to hypertriglyceridemia." (PMID 24566437, 2014). "One factor contributing to hypertriglyceridemia is the inability of insulin to inhibit the release of VLDL from the liver." (PMID 25411786, 2014).